CXCL13 (C-X-C motif chemokine ligand 13)
Diseases named in the same sentence as CXCL13 in open-access papers (continued):
Sharing a sentence is not in itself a finding about the gene and the disease.
lung carcinoma (continued). "Previous study has shown that tumor cells, follicular dendritic cells, and T follicular helper cells in lung cancer tissues are able to secrete chemokine, CXCL13, to attract B cells into the tumor tissue." (PMID 30521597, 2018). "The key carcinogen benzo(a)pyrene (BaP) induced CXCL13 production in lung epithelial cells and in mice prior to development of detectable lung cancer." (PMID 26565418, 2015). "By IHC assay, we found that both the Ttf1-positive lung cancer cells and Cd68-positive macrophages were stained positive for Cxcl13, but Ttf1-positive cells constituted more than 95% of the cellular component of the lung tumor tissues of the mice." (PMID 26565418, 2015). "Lastly, further experiments showed that CXCL13’s binding partner is highly expressed on some immune cells that can promote lung cancer." (PMID 26565418, 2015). "To determine the source of Cxcl13, we performed IHC and immunofluorescence assays in lung cancer tissues of the mice." (PMID 26565418, 2015). "We confirmed that BaP up-regulated CXCL13 at both the mRNA and protein levels in a dose- and time-dependent manner in 16HBE and A549 lung cancer cells." (PMID 26565418, 2015). "CXCL13-CXCR5 signaling was required for PAH-induced lung cancer, because knockdown of Cxcl13 or Cxcr5 attenuated BaP-induced lung cancer in mice." (PMID 26565418, 2015). "By treating 16HBE cells with a relatively low concentration (1 μM) of BaP for a long time course (30 days) to mimic BaP-induced lung cancer in humans, we showed that CXCL13 was the most significantly up-regulated gene among the 84 cytokines/chemokines." (PMID 26565418, 2015). "We found that CXCL13 was a direct target of AhR, and deficiency in CXCL13 or its receptor, CXCR5, abrogated BaP-induced lung cancer, while an anti-CXCR5 antibody significantly inhibited lung cancer cell migration." (PMID 26565418, 2015). "In addition, the CXCL13+CD4+ T cell subset indicated in lung cancer has been described by high expression of exhaustion markers, including PDCD1, CTLA4, TIGIT, and HAVCR2, which is considered as an exhausted CD4+ T cell subpopulation." (PMID 37187731, 2023). "Similarly in lung cancer the phenotypic and functional profiles of Tumour reactive T cells showed signs of exhaustion and CXCL13 production exclusively in Tumour infiltrating T cells and not in circulating peripheral T cells with shared specificity." (PMID 37520560, 2023). "The CXCL13 : CXCR5 axis might be involved in the promotion of lung cancer, and the B cell chemoattractant chemokine (CXCL13) is elevated in NSCLC patients, suggesting that it could be used as a predictor of the risk of early-stage lung adenocarcinoma." (PMID 36164329, 2022). "Anti-CXCL13 antibodies and RNAi were used to treat lung cancer and PDAC." (PMID 34947813, 2021). "In addition, a recent study also identified that CCL19, CCL20, and CXCL13 are highly expressed in lung cancer, and subsequent co-expression of CCL20 receptor CCR6 in CAR-T increased cell migration and tumor killing." (PMID 34553036, 2021). "Our present work reveals that CXCL13/CXCR5 axis could be a novel therapeutic target against lung cancer." (PMID 34427969, 2021). "Interestingly, the knockout of CXCL13 inhibits benzo(a)pyrene-induced lung cancer and azoxymethane/dextran sodium sulfate-induced colorectal cancer in mice." (PMID 34947813, 2021). "However, the prognostic value and pathological role of CXCL13/CXCR5 in lung cancer is still in its infancy." (PMID 34427969, 2021). "Therefore, we confirmed the activation of NF‐κB components after CXCL13 treatment in lung cancer cells." (PMID 34427969, 2021). "These evidences propose a novel insight into lung cancer metastasis which is regulated by CXCL13." (PMID 34427969, 2021). "There are several reports of CXCL13 expression in lung cancer." (PMID 32314548, 2020).
lung carcinoma (continued). "In addition, CXCL13 levels were increased in bronchoalveolar lavage fluid in non‐small cell lung cancer, and high CXCL13 was reported to be a poor prognostic factor." (PMID 32314548, 2020). "Furthermore, CXCL13 was increased in 134/201 (66.7%) NSCLCs, suggesting the clinical relevance of CXCL13 in BaP-induced lung cancer." (PMID 26565418, 2015). "In this study, we took the advantage of the epidemiology profile of Xuanwei lung cancer to systematically explore the abnormalities in inflammatory factors that are critical to air pollution-induced lung cancer, and reported that CXCL13 was up-regulated in 63/70 (90%) HPR NSCLCs." (PMID 26565418, 2015). "CXCL13 expression can be induced in various airway epithelial cells, pneumocytes, macrophages, and pulmonary reticular cells/fibroblasts in diverse inflammatory conditions such as allergic airway inflammation, environmental pollutant-induced lung cancer, and bacterial and viral infection." (PMID 34762185, 2022). "Besides, CXCL13+CD103+CD8+ TILs were potentially associated with B cell recruitment, neoantigen load and tertiary lymphoid structures (TLSs) formation in human tumors, and were identified as tumor antigen specific T cells in lung cancer." (PMID 36311750, 2022). "Therefore, we hypothesized that CXCL13‐induced lung cancer cell migration may be regulated by CXCR5." (PMID 34427969, 2021). "Here, we investigated whether CXCL13 activated these signalling pathways in lung cancer cells." (PMID 34427969, 2021). "It would be of great interest to determine whether lung cancer cells respond to CXCL13 by activating signaling pathways related to proliferation and survival, as this may reveal important direct effects of the chemokine resulting from paracrine or autocrine mechanisms." (PMID 31354634, 2019). "Previous studies have shown that CXCL13-expressing T cells facilitate B cell recruitment and TLS formation, leading to favorable prognoses in cancers such as breast and lung cancers." (PMID 40464813, 2025). "While our results support the utility of transcriptomic markers, other studies, particularly in lung cancer, have highlighted the importance of high clonal frequency in addition to CD39 protein and CXCL13 mRNA expressions in tumor-reactive T cells." (PMID 41294842, 2025). "Western blotting and qRT-PCR analyses were performed to quantify the expression levels of HER2, CXCL13, and CCL20 in the normal bronchial epithelial cell line BEAS-2B and several lung cancer cell lines (PC9, A549, H1734, H1975, H1299, and HCC827)." (PMID 40764989, 2025). "The results showed that the expression levels of CXCL13 and VTQ were significantly higher in the lung cancer group compared to the control group (P < 0.05)." (PMID 37025603, 2023). "The table summarizes the mean values, standard deviations, and statistical significance of the differences in CXCL13 and VTQ values between the lung cancer group and the control group." (PMID 37025603, 2023). "Our study found that the relative expression levels of CXCL13 and the VTQ values in the lung cancer group were significantly higher compared to those in the control group (P < 0.05)." (PMID 37025603, 2023). "Firstly, scRNA-seq study described a cellular module termed Lung Cancer Activation Module (LCAM), which was composed of PDCD1+CXCL13+ activated T cells, IgG+ plasma cells, and SPP1+ macrophages." (PMID 37187731, 2023). "Meanwhile, they also indicated that PLCβ, PKCα and c-Src signaling pathways also participated in CXCL13-promoted cell migration and VCAM-1 expression in lung cancer cells." (PMID 37393391, 2023). "Compared with healthy controls, the levels of CXCL14, CXCL13 and CCL20 were increased in the plasma of patients with lung cancer." (PMID 35769715, 2022). "For instance, expression of CXCL13 and/or CXCR5 correlates significantly with tumorigenesis, and CXCL13 is considered a predictive factor for lung cancer progression and early diagnosis." (PMID 35702353, 2022).
lung carcinoma (continued). "Increased expression of CXCL13 was found in several types of airway diseases, such as COPD and lung cancer." (PMID 35165593, 2022). "The results indicated treatment with recombinant CXCL13 dramatically increased migration and invasion of CL1‐0 lung cancer cells." (PMID 34427969, 2021). "In this study, we found that CXCL13 and CXCR5 were commonly up‐regulated in lung cancer specimens compared with normal tissues among different cohorts." (PMID 34427969, 2021). "We found that expression levels of CXCL13 and CXCR5 were highly correlated with lung cancer progression." (PMID 34427969, 2021). "Here, we report the prognostic relevance of CXCL13/CXCR5 and found that they are commonly overexpressed among different subtypes of lung cancer." (PMID 34427969, 2021). "Here, we also investigated the correlation between CXCL13 and VCAM‐1 in tissues of lung cancer patients." (PMID 34427969, 2021). "On the other hand, CXCL13 recruits CXCR5+ CD68+ macrophages secreting SPP1, which triggers tumor cell migration through the EMT pathway in lung cancer." (PMID 34947813, 2021). "The results indicated that pre‐treatment with PLCβ, PKCα and c‐Src inhibitors (U73122, GF109203X and PP2) reversed CXCL13‐promoted cell migration and VCAM‐1 in lung cancer cells." (PMID 34427969, 2021). "Here, we found that expression levels of CXCL13 and CXCR5 were highly correlated with lung cancer progression." (PMID 34427969, 2021). "Here, we found that Src was activated by CXCL13/CXCR5 axis and subsequently regulated cell migration in lung cancer cells." (PMID 34427969, 2021). "An inflammation score based on CXCL13 and three additional markers (CRP, MDC/CCL22, and IL-1RA) provided good separation in 10 year cumulative risks of lung cancer." (PMID 31354634, 2019). "Notably, all lung cancer cell lines exhibited elevated protein expression of CXCL13 and CCL20, with CXCL13 being approximately three times higher in H1975, H1299, and HCC827, and CCL20 being more than twice as high in A549, H1734, H1975, and HCC827." (PMID 40764989, 2025). "Here authors show that mutation-associated neoantigen-specific CD8+ tumor-infiltrating lymphocytes can be recognized by MANAscore, an algorithm that uses weighted expression levels of CXCL13, ENTPD1 and IL7R in single-cell RNAseq datasets of lung cancer and melanoma patients as input." (PMID 39900903, 2025). "The results of the study showed that both the expression levels of CXCL13 and VTQ were significantly higher in the lung cancer group compared to the control group (P < 0.05), which suggests that the sample size was sufficient to detect a significant difference between the two groups." (PMID 37025603, 2023). "By comparing these values, we can understand the relationship between the expression levels of CXCL13 and the VTQ results, and how they may be used as indicators of lung cancer." (PMID 37025603, 2023). "Highly expressed CXCL13 and CXCL14 in lung cancer tissues were also reported in other studies." (PMID 35844446, 2022). "Moreover, CXCL13 and CXCL13+ immune cells in the TME of nonsmall cell lung cancer strongly predicted patients’ response to anti‐PD‐1 therapy, correlating with improved durable response and prolonged OS." (PMID 35702353, 2022). "Finally, PLCβ, PKCα and c‐Src signalling pathways were involved in CXCL13‐promoted cell migration and VCAM‐1 expression in lung cancer cells." (PMID 34427969, 2021). "We also test the candidate components which are activated after CXCL13 treatment and found that phospholipase C‐β (PLCβ), protein kinase C‐α (PKCα) and c‐Src signalling pathways were involved in CXCL13‐promoted cell migration and VCAM‐1 expression in lung cancer cells." (PMID 34427969, 2021). "Finally, we manipulated online gene expression profiling tool GEPIA 27 to assess the correlation between CXCL13 and VCAM‐1 in lung cancer tissues." (PMID 34427969, 2021).
lung carcinoma (continued). "Surprisingly, with meta‐analysis in all lung cancer tissues containing adenocarcinoma (LUAD) and squamous‐cell carcinoma (LUSC), we found consistent up‐regulation of CXCL13 and CXCR5 in multiple lung cancer studies, suggesting the impact of CXCL13‐CXCR5 axis in lung cancer progression." (PMID 34427969, 2021). "In regard to the key role of Src in tumour progression, combination therapy of CXCL13/CXCR5 axis and Src inhibitors may provide clinical benefits in lung cancer treatment." (PMID 34427969, 2021). "The cell viability assay showed no statistical significance after CXCL13 incubation in lung cancer cells." (PMID 34427969, 2021).
melanoma (49 papers, 2013 to 2026). A malignant, usually aggressive tumor composed of atypical, neoplastic melanocytes. "Above all, CD8+ T cells were present in melanomas with a high mutation load, and they did not only express CXCL13 but also exhaustion markers (e.g., PD-1)." (PMID 36836910, 2023). "Together these data suggest that 3-component index that integrates high expression of APRIL/TNFSF13, CXCL10, and CXCL13 transcripts in tumor are associated with superior melanoma patients' survival and a pro-inflammatory TME supportive of LA and /or TLS." (PMID 37435077, 2023). "A 12-chemokine gene expression signature including CCL2-5, CCL8, CCL18, CCL19, CCL21, CXCL9-11, and CXCL13 has been previously reported to serve as a predictor for the presence of TLS in melanoma specimens in association with improved OS." (PMID 37435077, 2023). "Melanoma differentially expressed genes positively associated with high APRIL/CXCL10/CXCL13 tumor expression were linked to tumor infiltration by a diverse array of proinflammatory immune cell types." (PMID 37435077, 2023). "We found that the presence of B cells (CD19+) or B cell chemokine CXCL13 in tumors was associated with improved overall survival among melanoma patients." (PMID 35720386, 2022). "Given the cancer‐promoting role of M2 macrophages, we investigated the impact of CXCL13 on melanoma cells." (PMID 40692663, 2025). "Consistent with previous research, our findings indicate that CXCL13 facilitates both melanoma cell invasion and metastasis while also promoting immune evasion by modulating the expression of MMP9 and PD‐L1 in tumor cells." (PMID 40692663, 2025). "AIGPS also captures melanoma-specific regulatory mechanisms through its selected gene pairs (e.g., CXCL13-TNFRSF9 and CDK1-RB1), such as chemokine signaling pathway, cytokine-cytokine interaction, and retinoblastoma in cancer." (PMID 40917881, 2025). "Transcriptomic analysis further revealed that lactate induces C‐X‐C motif chemokine ligand 13 (CXCL13) expression in macrophages, which enhances melanoma invasiveness and impairs immune cell‐mediated cytotoxicity." (PMID 40692663, 2025). "The presence of B cells (CD19+) or the chemokine CXCL13 in tumor tissue has been correlated with improved overall survival (OS) in melanoma patients." (PMID 40636453, 2025). "Crizotinib inhibits CD147‐MCT1‐mediated lactate transport, suppressing melanoma growth and immune escape, prevents M2 macrophage polarization, and enhances immunotherapy by reducing CXCL13 via histone lactylation." (PMID 40692663, 2025). "CXCL13 was found to be preferentially enriched in dysfunctional CD8+ T cells within the melanoma ecosystem, and together with TIGIT, PDCD1 and LAG3, it has been used to define the dysfunctional state of T cells." (PMID 38519500, 2024). "We observed that melanoma patients with coordinately high serum levels of APRIL and coordinate high APRIL/CXCL10/CXCL13 we're associated with improved survival and proinflammatory TME." (PMID 37435077, 2023). "Each of the individual TLS-kines were significantly positively correlated with levels of melanoma infiltration by CD8+ T cells, with CXCL13 having the strongest association (r = 0.7)." (PMID 37435077, 2023). "Metastatic melanoma patients with a high CXCL13 expression in tumor tissue showed a better overall survival." (PMID 36836910, 2023). "Our study highlights the potential of CXCL13 and B cell based strategies to enhance the rate of durable response in melanoma patients treated with ICI." (PMID 37435085, 2023). "In this melanoma sample, expression of genes associated with the terminally differentiated phenotype of CD8+ T cells, such as HAVCR2 (TIM-3), LAG3, CXCL13, and GZMB, was highest in the tumor parenchyma adjacent to inflammation." (PMID 35584630, 2022). "Among them, in the studies of “Kim2018 PD1 Gastric” (AUC=0.85) and “Gide2019 PD1 Melanoma” (AUC=0.83), the CXCL13 predictive power of response outcome was better than other published biomarkers." (PMID 35141160, 2022).